ERBB2 (erb-b2 receptor tyrosine kinase 2)
Diseases named in the same sentence as ERBB2 in open-access papers (continued):
Sharing a sentence is not in itself a finding about the gene and the disease.
ovarian carcinoma (continued). "ERBB2 gene enrichment was correlated with a poor prognosis of cancer patients in some primary tumors, such as glioblastoma, low-grade glioma, ovarian cancer, and skin cutaneous melanoma." (PMID 36172165, 2022). "Six of these also efficiently reversed the ErbB2-induced “invasive” distribution of lysosomes in SKOV3ip1 ovarian cancer cells." (PMID 33939112, 2021). "It has been recently shown that increased cell sialylation induced lower response of GC cells to the anti-ErbB2 monocolonal antibody trastuzumab as well as reduced response of ovarian cancer cells to the EGFR TKI gefitinib." (PMID 31979110, 2020). "Tumor-specific targeting and retention were achieved by genetic modification of MSCs with AR against EGFRvIII in GBM and erbB2 in ovarian cancer." (PMID 30464207, 2020). "ERBB2, the second ErbB-family member, is ubiquitously expressed and commonly altered in metastatic breast, prostate and ovarian cancers." (PMID 32595631, 2020). "A variety of tumors has been positively analyzed for ErbB2 overexpression or gene amplification: non-small-cell lung cancer, ovarian cancer, bladder cancer, pancreatic cancer, and salivary duct carcinoma." (PMID 32423101, 2020). "Ovarian cancer cells with ErbB2 amplification (OVCAR8 and SKOV3ip1) were the most sensitive to Grb2 downregulation." (PMID 32754300, 2020). "The prognostic value of ERBB2 in ovarian cancer has been recently evaluated in 5,180 ovarian cancer patients and was negatively correlated with overall survival outcome." (PMID 33424936, 2020). "Exposure of sarcoma and PDX ovarian carcinoma cells to [pazopanib + entinostat] caused a prolonged activation of ERBB1 and transient/prolonged activations of ERBB2, c-KIT, and c-MET, in a cell-specific fashion." (PMID 31380285, 2019). "Amplification of ErbB2 (HER2) occurs in 28% of ovarian cancers, representing a potential therapeutic target in this subset of ovarian cancer patients." (PMID 29435137, 2018). "HA mediates the action of physical linkage between CD44s and Her2/ErbB2 tyrosine kinase, which results in the rapid stimulation of ovarian carcinoma cell growth." (PMID 29510526, 2018). "Although breast and ovarian cancer have comparable levels of HER2/ErbB2 expression patterns, pertuzumab treatment is more effective in BC." (PMID 30211115, 2018). "The cells after hyaluronan stimulation throughout CD44 produce TGFbeta and bFGF and in ovarian cancer model CD44 interacts with Her2 and ErbB2 in presence of hyaluronan inducing cell growth." (PMID 29023465, 2017). "Overexpression of TFAP2A and ERBB2 was observed on the mRNA level in relation to other ovarian cancer subtypes." (PMID 28611940, 2017). "ERBB2 p.V842I and EP300 p.R1312X mutations have been reported in colon and ovary cancers, respectively." (PMID 28179590, 2017). "In ERBB2 (Her2/Neu) overexpressing ovarian cancer cells, the stable silencing of NRF2 repressed ERBB2 expression and its downstream signaling and retarded tumor growth." (PMID 26682001, 2016). "It is also possible that ERBB2 isoforms function in a kinase independent manner in ovarian cancer cells." (PMID 27558154, 2016). "HER2 (also known as ERBB2 or NEU) is an internalizing cell surface receptor overexpressed or mutated in a variety of solid tumors including breast, gastric, lung and ovarian cancers." (PMID 26840082, 2016). "In ovarian cancer cells the level of ErbB-2 expression positively correlates with the level of p66Shc." (PMID 25890053, 2015). "The present study was designed to explore the cross talk between fatty acid synthase (FASN) and HER2 (ErbB2) in ovarian cancer." (PMID 25433947, 2015).
ovarian carcinoma (continued). "ERBB2 (HER2) amplification, predicting sensitivity to anti-HER2 therapy was also observed in our cohort in breast, colorectal, lung and ovarian cancer samples." (PMID 25889064, 2015). "Expression of the related ErbB2/HER2 transmembrane tyrosine kinase has been reported in ovarian cancer." (PMID 26336133, 2015). "One of the histological and molecular subtypes of ovarian cancer is low-grade serous (LGS) ovarian carcinoma characterized by BRAF, KRAS, NRAS and ERBB2 mutation, amplification or overexpression." (PMID 25408231, 2014). "Next to BCL3, ERBB2/3 (Her2/Her3) are also downregulated upon miR-125b overexpression in human ovarian cancer cell lines, further demonstrating that this pathway is involved in the development of multiple tumor types in which miR-125b is tumor suppressive." (PMID 24774301, 2014). "The EC1-GLuc-liposome effectivly targeted ErbB2-overexpressing ovarian cancer cells for bioluminescence imaging in vitro and in vivo, and also proved to be effective in targeted DDS." (PMID 25190023, 2014). "To validate our method further, we applied ONCOCNV to analyze amplicon sequencing data generated for 30 ErbB2-positive ovarian cancer samples." (PMID 25016581, 2014). "Strikingly, ERBB2/3 has been shown to be upregulated in ovarian cancer tissues, suggesting enhanced angiogenenesis upon miR-125b downregulation in this tumor entity." (PMID 24774301, 2014). "The human epidermal growth factor receptor 2 (HER2, also known as ErbB2/c-erbB2/HER2-neu), a transmembrane receptor tyrosine kinase, is overexpressed in 25–30% of breast cancers and 6–50% of epithelial ovarian cancers." (PMID 22879947, 2012). "Mutations in BRAF, KRAS, and erbB2 oncogenes and in the tumor suppressor PTEN have been found in a large subset of ovarian cancers." (PMID 22481926, 2012). "Consistent with this feature, EGFR and ErbB2 phosphorylation was inhibited for more than 24 h after AST1306 treatment in the SK-OV-3 human ovarian carcinoma xenograft model." (PMID 21789172, 2011). "Anti-ERBB2 Trastuzumab and lapatinib inhibited the proliferation and tumor growth in ovarian cancers with ERBB2 upregulation." (PMID 21962244, 2011). "For example, in ovarian carcinoma cell lines, p66Shc protein level positively correlates with ErbB-2 expression, a prognostic marker for ovarian cancer." (PMID 21264241, 2011). "ERBB2 overexpression and amplification are present in a subset of epithelial ovarian cancer and serous carcinoma." (PMID 21962244, 2011). "Overall, our data validates previously known ovarian cancer genes, such as ERBB2, and also identified novel potential drivers such as MYNN, PUF60 and TPX2." (PMID 20386695, 2010). "Amplification of ErbB2 protein is found in approximately one third of ovarian cancers and is an indicator of poor prognosis in advanced disease." (PMID 20224651, 2010). "In a study of 837 patients with recurrent or chemorefractory ovarian cancer treated with trastuzumab, a response rate of 7% was obtained in 47 patients with ErbB2 overexpressing tumours." (PMID 24281034, 2010). "Early studies have demonstrated comparable levels of HER2/ErbB2 expression in both breast and ovarian cancer." (PMID 20346177, 2010). "Pertuzumab, another humanised monoclonal antibody that inhibits dimerization of ErbB2 with other EGFRs has shown unexceptional activity in recurrent ovarian carcinoma with response rates under 5% when administered as a single agent." (PMID 24281034, 2010). "Overexpression of EGFR (ErbB1) and HER2-neu (ErbB2) has been reported in ovarian cancer and both receptors are commonly co-expressed." (PMID 18182111, 2008).
ovarian carcinoma (continued). "In previous studies, β-HCH has been shown to activate c-Neu (also known as erbB2 or HER2) kinase in breast epithelial cells and ovarian cancer cells." (PMID 17640349, 2007). "The low-ERBB2-expressing ovary cancer cells, OVCAR-3, showed an increase of the LUC activity with the promoter size." (PMID 12942124, 2003). "ERBB2 is overexpressed in about 30% of breast and ovary cancers and this has been correlated with poor prognosis for the patient." (PMID 12942124, 2003). "The transcriptional activity of the ERBB2 promoter in colon and ovary cancer cells was estimated using reporter vectors." (PMID 12942124, 2003). "In SK-OV-3 ovary cancer cell line, overexpressing about 60 times the erbB-2 transcript, only the p756-LUC vector induced a significant increase in the transcription level (compare lanes 1 and 2)." (PMID 12942124, 2003). "Human ovarian carcinoma SKOv3 cells that express a high level of ErbB2 were transfected with the CEA cDNA." (PMID 11742503, 2001). "To elucidate whether baicalein inhibits the growth of aggressive ovarian cancer cells, we first assessed the cell viability of highly invasive human SKOV-3 and TOV-21G ovarian cancers with different ErbB2 levels treated with baicalein." (PMID 36770705, 2023). "Similarly, ERBB2 (Receptor tyrosine-protein kinase erbB-2) is upregulated in breast, esophageal, gastric, and ovarian cancer." (PMID 35163434, 2022). "We have also shown for the first time in ovarian cancer cells that poziotinib, currently in late phase clinical trials for patients with NSCLC and an ERBB2 exon 20 insertion mutation, has a similar effect when combined with paclitaxel in ABCB1-overexpressing ovarian cancer cells." (PMID 34347777, 2021). "The ERBB2 rs28933370 missense mutation was reported as being pathogenic/likely pathogenic from ovarian cancer with somatic allele origin, while neither ascertain criteria nor alternative allele frequency from 1000 Genomes or the Taiwan Biobank were provided." (PMID 34203389, 2021). "Moreover, ERBB2 activation was reported as one of the key pathways in cisplatin-resistance in ovarian cancer." (PMID 35070983, 2021). "There are several findings on ERBB2 gene amplification, also commonly known as member of the epidermal growth factor receptor family, in multiple tumor types including early endometroid uterine cancer and ovarian cancer." (PMID 33424936, 2020). "The EGF receptor (EGFR) (or HER) proto-oncogene family consists of four transmembrane tyrosine kinase receptors (i.e., EGFR, ErbB2, ErbB3, and ErbB4) that play a role in cancer pathogenesis and has been described as key therapeutic target in many types of cancer, including ovarian cancer." (PMID 32039018, 2019). "We have previously shown that lapatinib, an EGFR/ErbB2 kinase inhibitor, inhibits invasion and alters the lysosomal distribution from predominantly peripheral to predominantly perinuclear in ErbB2-positive ovarian cancer cells." (PMID 29396433, 2018). "ErbB-2-specific antibodies and T cells are detectable in patients with breast and ovarian cancers, suggesting that erbB-2 could be a target for immunotherapy." (PMID 28460461, 2017). "However, upregulation of ERBB2 alone was insufficient to enhance cell proliferation and survival of ovarian cancer cells." (PMID 28439256, 2017).
ovarian carcinoma (continued). "Indeed, cancerous ovaries of hens show very similar patterns of expression of tumor-related genes compared with those in women, and high cross-reactivity and expression of biomarkers such as CA125, EGFR, and ERBB-2 for human ovarian cancer." (PMID 22496782, 2012). "17-AAG may sensitize a subset of ovarian cancer to paclitaxel, particularly those tumors in which resistance is driven by Hsp90 clients such as ERBB2 and/or p-Akt." (PMID 20078855, 2010). "Likewise ErbB2 (also named HER2) overexpression is found in only a minority of ovarian carcinomas (5%)." (PMID 24281034, 2010). "Our results suggest that the currently applied criteria for ERBB2 overexpression in ovarian cancer (i.e. 2+ and 3+) are too restrictive and from the clinical viewpoint it would be justified to include any ERBB2 membranous expression in above 10% of the tumour cells to positivity (or overexpression)." (PMID 15545967, 2004). "With the methods applied, we have possibly identified subgroups of ovarian cancer patients who may benefit from anti-ERBB2 therapy, and timing of such a therapy." (PMID 15545967, 2004). "Another possibility is that other regulatory elements, located outside the promoter region tested in this study, could influence ERBB2 expression in colon and ovary cancer cells." (PMID 12942124, 2003). "In addition, ERBB2 is widely expressed in ovarian cancer, cervical cancer, and uterine sarcoma." (PMID 40046734, 2025). "The HER2-encoding gene ERBB2 has been found to be amplified or overexpressed in various cancers, including breast, gastric, colorectal, esophageal, lung, bladder, endometrial, and ovarian cancers, which makes this membrane-bound protein an effective target for cancer therapy." (PMID 38796692, 2024). "Furthermore, our data suggested CRTC2 and ERBB2 behaved as oncogenes in ovarian cancer." (PMID 37845675, 2023). "In addition, potential targetable amplifications were detected, i.e. high level amplifications of ERBB2 (colorectal carcinoma, salivary duct carcinoma, prostate cancer, ovarian cancer), MET (lung cancer, esophageal carcinoma), and FGFR1 (lung cancer, colorectal carcinoma)." (PMID 32264863, 2020). "Interestingly, the ADC ST8176AA1 here described appears to inhibit tumor growth without inducing toxicity and it could therefore be an attractive opportunity for patients with ErbB2+ ovarian cancer." (PMID 32039017, 2019). "Interestingly, it has been reported that the level of VEGF in serum may depend on the expression of ErbB2 in patients with ovarian cancer." (PMID 29482638, 2018). "Therefore, the specific regulation of ErbB2 in ovarian cancer remains to be studied further." (PMID 29482638, 2018). "Moreover, since ErbB2 is also known to play a major role in other cancers, such as ovarian cancer, it is possible that nucleolin might be involved in ErbB2 activation in this disease as well, and might affect the progression of this malignancy." (PMID 27542246, 2016). "Human epidermal growth factor receptor 2 (HER2), also known as ERBB2, is a transmembrane tyrosine kinase receptor overexpressed in several solid cancers including ovarian cancer." (PMID 38667465, 2024). "Otherwise, KRAS, ERBB2, and RHOA are all in connection with ovarian cancer, but little is known about the mechanisms involved in other ovarian functional regulation of these genes, and there are also only a few exosomal miRNA-related pieces of research." (PMID 38037065, 2023). "Region 20q13.12, previously identified in other ovarian tumors, was amplified in our cohort, along with other genes that have previously found amplified in ovarian cancer such as CCNE1, ERBB2, RSF1 and deleted genes like BRCA18,22." (PMID 37400526, 2023).
ovarian carcinoma (continued). "Rearrangements of the ERBB2 gene have been found in breast as well as gastric cancers and ERBB4 fusions have been reported in lung adenocarcinomas and ovarian cancer cell lines." (PMID 37168365, 2023). "In the endometrial and ovarian cancer cell lines ECC-1 and HCH-1, respectively, FCF decreases the expression of HER2 (human epidermal growth factor receptor 2; human gene symbol: ERBB2), a protein which is often overexpressed in certain tumor types." (PMID 35409322, 2022). "The evidence suggested that berberine consumed EGFR and ERBB2 in ovarian cancer cells and inhibited the activation of EGFR and ERBB2 downstream targets cyclin D1, MMPs, and VEGF via the EGFR-ERBB2/PI3K/Akt signaling pathway." (PMID 35889396, 2022). "We constructed a CAR that targets the ErbB2/HER2 protein (ErbB2CAR), which is overexpressed in HGSOC, and evaluated the functionality of ErbB2CAR on ovarian cancer cell lines (OVCAR8, SKOV3, and NAR)." (PMID 36140319, 2022). "About 11% of ovarian tumors have ErbB2 amplification, whereas EGFR overexpression is found in up to 28% and amplified in up to 20% of ovarian cancers." (PMID 32754300, 2020). "In PDX isolates of ovarian cancer cells, however, the expression and phosphorylation of ERBB1, ERBB2, c-MET, c-KIT, and c-SRC was reduced by drug combination exposure." (PMID 31380285, 2019). "In conclusion, hub genes (such as TGFA, EGFR, ErbB2, and MYC) and key pathways (such as the ErbB signaling pathway) closely related to the proliferation of ovarian cancer cells in hypoxia were identified by bioinformatics analysis." (PMID 29482638, 2018). "Among the most interesting cases are the rare germline CNVs affecting RET in GBMs, ERBB2 in renal cell carcinomas, and DCC in ovarian cancers." (PMID 25644941, 2015). "One possible chemotherapeutic target of ovarian cancers would be the inhibition of the tyrosine kinase receptors, ErBb1 (EGFR) and ErBb2 (Her-2)." (PMID 26617640, 2015). "Our previous study showed that miR-199a inhibits tumor angiogenesis by targeting ERBB2 and ERBB3 thus suppressing their downstream VEGF in ovarian cancer cells." (PMID 24413338, 2014). "Our results suggested that the simultaneous activation of multi-RTK (EGFR, ERBB2, ERBB4, MET and/or AXL) in individual ovarian cancer contribute to the drug resistance to individual RTK inhibitors in ovarian cancer." (PMID 21962244, 2011). "Herein, we demonstrate co-activation of multiple RTKs (EGFR, ERBB2, ERBB4, MET and/or AXL) in individual ovarian cancer cell lines and primary tumors." (PMID 21962244, 2011). "The HSP90 inhibition led to the dephosphorylation and degradation of EGFR, ERBB2, ERBB4, MET and AXL in various ovarian cancer cells." (PMID 21962244, 2011). "Currently, the mostly investigated targets in ovarian cancer are (VEGF) and (EGFR) family members (EGFR1, EGFR2/ErbB2)." (PMID 22235224, 2011). "Immunoblotting evaluations of ovarian cancer total cell lysates also demonstrated inactivation of EGFR, ERBB2, and MET after 17-AAG treatment." (PMID 21962244, 2011). "Inhibition of total EGFR, ERBB2, MET and AXL expression was seen in all ovarian cancer cell lines after treatment with 17-AAG in serum-containing medium for 48 hours." (PMID 21962244, 2011). "Our studies demonstrated that simultaneous activation of multi-RTKs including EGFR, ERBB2, MET, and AXL contributes to ovarian cancer cell proliferation and survival." (PMID 21962244, 2011). "In the current studies we demonstrate the simultaneous activation of multiple RTKs - including EGFR, ERBB2, MET, and/or AXL - in individual ovarian cancer cell lines and primary tumors." (PMID 21962244, 2011). "It has been suggested that this protein acts downstream of the ERBB2 pathway, since phosphorylation of SFRS9 was detected in ERBB2-over expressing breast and ovarian cancer cells and was reduced by monoclonal antibody Herceptin treatment." (PMID 21210970, 2010).